NOTCH1 (notch receptor 1)
Diseases named in the same sentence as NOTCH1 in open-access papers (continued):
Sharing a sentence is not in itself a finding about the gene and the disease.
leukemia (continued). "The most prevalent human leukemia-associated NOTCH1 mutations occur in the heterodimerization domain of the NOTCH1 negative regulatory region." (PMID 27106930, 2016). "Notch1 is strongly associated with tumor progression in patients with leukemia or T-cells lymphoma and crosstalks with c-myc pathway." (PMID 26993595, 2016). "SERCA inhibition induces a G0/G1 arrest in NOTCH1-mutated human leukemia cells, introducing SERCA as a potential therapeutic target in cancers associated with NOTCH1 mutations." (PMID 25852478, 2015). "This malignancy was associated with upregulation of Notch1 mRNA and protein before frank leukaemia was observed." (PMID 23667468, 2013). "As NOTCH1 activating mutations are present in >50% of human T-ALL; exons 26, 27 and 34 which are the common sites of Notch1 mutational activation in murine leukemias were sequenced from Sdl tumors." (PMID 23133403, 2012). "Comprehensive profiling of TSPAN32 expression across genetically annotated patient cohorts will be necessary to delineate the precise relationship between leukemia subtype, underlying mutations (e.g., NOTCH1, FBXW7, PHF6, HOXA cluster abnormalities), and TSPAN32 regulation." (PMID 41007654, 2025). "Cooperation between KRAS and NOTCH in T-ALL was directly demonstrated by Pear and colleagues in studies showing that NOTCH1 GOF alleles found in T-ALL patients efficiently generate leukemia in mice when overexpressed in transplanted BM HPCs expressing KrasG12D but not in wild-type BM HPCs." (PMID 36674902, 2023). "A previous study reported that Vegfa and Il1b transcripts are elevated in leukemia-associated macrophages in a NOTCH1-induced model of T-ALL54, suggesting secreted myeloid factors could promote FAK/PYK2 activation in T-ALL cells." (PMID 37805579, 2023). "However, the proportion of NOTCH1 mutation seems to be higher in SET-CAN/NUP214 positive leukemia patients." (PMID 37909026, 2023). "To determine whether DKO leukemias also had mutations in the Notch1 gene, we PCR amplified the 3’ portion of Notch1 and performed sequencing on 3 DKO cell lines that we established in culture." (PMID 35371057, 2022). "While it remains to be seen if similar mechanisms are operational in leukemia, the synergy observed in our study could be broadly applicable to tumors beyond NOTCH1-mutated ALL." (PMID 35589701, 2022). "These leukemia subtype has a high prevalence of NOTCH1 mutations." (PMID 34440292, 2021). "The mutational status of Notch1/FBXW7 genes may influence the response of leukemia patients to treatment protocols including cyclophosphamide." (PMID 34680255, 2021). "In T cell acute lymphoblastic leukemia (leukemia), loss of PRC2 core subunits was reported to occur by mutation or deletion in about 25% of all cases, and in a NOTCH1-induced genetic mouse model of leukemia, NOTCH1 antagonizes PRC2 function, leading to a loss of H3K27me3." (PMID 32651197, 2020). "This is a high-risk leukemia known for frequent mutations in the NOTCH1 gene." (PMID 33374919, 2020). "Interestingly, most of these leukemias also acquired somatic Notch1 mutations, which are highly prevalent in human T-ALLs and have also been observed in other murine models of T-ALL." (PMID 31199785, 2019). "This cell line may be useful as a model system for dissecting the signaling pathways implicated in T-ALL survival and growth independent from NOTCH1 and for the screening of targeted anti-leukemia agents specific for this T-ALL subgroup." (PMID 30304769, 2018). "We demonstrated that the presence of subclonal NOTCH1 mutations from early phases of the disease affected patient survival, providing a proof-of-principle that very few leukemia subclones detected at diagnosis are important drivers of the subsequent disease course." (PMID 29998084, 2018).
leukemia (continued). "CXCR4 expression was found to be essential for T-ALL maintenance and progression with loss of CXCL12/CXCR4 signaling leading to reduced Myc expression (a transcription factor directly regulated by NOTCH1) and previously linked to leukemia initiating cell activity in T-ALL." (PMID 29666622, 2018). "Prdm14 misexpression could also promote RAG-dependent driver mutations at loci other than Notch1 in lymphoid cells to cause the other lymphoid-lineage leukemias we previously observed in other PRDM14-induced models." (PMID 27106930, 2016). "Mutation in Notch1 has been implicated in the pathogenesis of Leukemias." (PMID 24688641, 2012). "Moreover, certain mutations that constitutively activate Notch1 protein cause leukaemia; although this is usually T-cell acute lymphoblastic leukaemia rather than the AML associated with Prdm16." (PMID 19050759, 2008). "Moreover, in leukemia cells expressing native Np9, the protein was shown to co-activate multiple leukemia-associated signaling pathways, inducing an aberrant upregulation of pERK, c-Myc and β-catenin and cleaving Notch1 with a subsequent decrease of Numb." (PMID 29593697, 2018). "In T‐cell acute lymphoblastic leukemia (T‐ALL), a dependency of GS levels on Notch1 activity was demonstrated with consequences in glutamine metabolism and survival both in vitro and in a Notch1‐driven leukemia mouse model." (PMID 38105543, 2025). "The conditional deletion of the Klf4 gene accelerated leukemia in the NOTCH1-induced T-ALL mouse model, increasing both the proliferation of T-ALL cells and the frequency of leukemia-initiating cells (LIC) measured in a limiting dilution transplantation study." (PMID 40589762, 2025). "High MYC and CD34 expression define T-ALL cells with leukemia-initiating cell (LIC) properties in activated NOTCH1-driven T-ALL13,66." (PMID 40319015, 2025). "T‐ALL includes canonical T‐ALL, characterised by frequent NOTCH1 mutations and an immature T‐cell phenotype, and early T‐lineage progenitor (ETP) leukaemia, characterised by frequently expressing stem cell and myeloid cell‐surface markers." (PMID 40754682, 2025). "During the initiation and progression of leukemia, there is a connection between the recruitment of NOTCH1 to target genes and the reduction of H3K27me3 levels, which occurs through the action of the enzyme Jumonji D3 (JMJD3)." (PMID 39048945, 2024). "A previous work that focused on chronic lymphocytic leukemia suggested a role for ER stress in Notch1 cleavage and leukemia cell death through the inhibition of proteasome activity." (PMID 39258755, 2024). "Our previous study demonstrated that USP7 interacts with NOTCH1 and controls leukemia growth by stabilizing the levels of NOTCH1." (PMID 38007584, 2024). "In keeping with this, CIMP leukemias also exhibited increased methylation at NOTCH1, MYB, and TAL1 binding sites than ETP-ALL, and hypomethylation of TFBS for myeloid master regulators such as CEBPA, CEBPB, and SPI1." (PMID 38972954, 2024). "High MYC and CD34 expression define T-ALL cells with leukemia-initiating cell (LIC) properties in activated NOTCH1-driven T-ALL5,17,66,67." (PMID 38352301, 2024). "We have previously identified a specific chemovar of Cannabis that induces apoptosis by preventing Notch1 maturation in leukemia cells." (PMID 39258755, 2024). "Both leukemia samples exhibited expression of active/cleaved NOTCH1, which responded to gamma-secretase inhibitor treatment." (PMID 38553571, 2024). "In contrast, the SERCA inhibitor CAD204520 demonstrates reduced Ca2+-related toxicity and yet retrains its anti-NOTCH1 effect, which made it an ideal compound for assessing the relevance of NOTCH1 in MLLr leukemia in this study." (PMID 37833915, 2023). "NOTCH1 has been proven to act as a promoter for a MYC enhancer that promotes T cell development in leukemia." (PMID 37072406, 2023).
leukemia (continued). "Using flow cytometry, we demonstrated that cytarabine did not induce a reduction in NOTCH1 receptors, unlike CAD204520, which reinforces CAD204520’s specificity toward MLLr leukemia cells via NOTCH1." (PMID 37833915, 2023). "In leukemia, Olig2 seems only oncogenic in thymocytes and collaborative with LMO1 and Notch1 to induce highly penetrant leukemia." (PMID 36990974, 2023). "In this study, we demonstrated the relevance of NOTCH1 in MLLr leukemia by using the NOTCH1 inhibitor CAD204520." (PMID 37833915, 2023). "In this study, we identified NOTCH1 as a driver of MLLr leukemogenesis, suggesting the potential to use this target as a molecular-guided treatment approach for MLLr leukemia." (PMID 37833915, 2023). "Common mutations found in leukemia patients, such as ABL1, FGFR1, KRAS, MET, NOTCH1, and PTPN11, were also found among our patient population, although not universally." (PMID 37092520, 2023). "To establish a connection between our model-based analysis and the clinic, we also analyzed patient samples with MLLr leukemia using RT-qPCR, which revealed significant NOTCH1 overexpression compared with huCB-derived CD34+ cells." (PMID 37833915, 2023). "Consistent with NOTCH1 expression and activation, Notch1 and cMyc genes were abundantly expressed in all primary leukemia samples." (PMID 36765626, 2023). "Then, it is proved that adipocytes attract T‐ALL cells by releasing CXCL13 and support leukemia cell survival by activating the Notch1 signaling pathway via DLL1 and Notch1 binding." (PMID 37072664, 2023). "Mutational screening uncovered the presence of secondarily acquired NOTCH1 mutations, located in the PEST domain and/or the overexpression of NOTCH1, in 100% of mice, which correlated with a high level of transplantability of these leukemias." (PMID 36674902, 2023). "Recently, the SERCA inhibitor CAD204520 with reduced off-target toxicity has been established, which allows us to investigate the relevance of the NOTCH1 pathway and its therapeutic consequences in MLLr leukemia." (PMID 37833915, 2023). "In agreement, both in vitro and in vivo, the greatest effect on leukemia growth reduction was achieved by anti-NOTCH1 therapy in combination with antimetabolite drugs." (PMID 37667380, 2023). "In conclusion, our findings uncover the oncogenic relevance of the NOTCH1 pathway in MLLr leukemia and provide a promising target in the treatment of MLLr leukemia." (PMID 37833915, 2023). "The abnormality of NOTCH signaling is related to esophageal cancer, gastric cancer, leukemia and other diseases, Among them, abnormal NOTCH1 is most often detected in tumor diseases." (PMID 37909026, 2023). "In mouse tal1 tumour cell lines, leukaemia growth/survival remains dependent on the NOTCH1-c-MYC pathway; accordingly, the oncogenic functions of c-MYC and NOTCH1 have been established and a direct connection between NOTCH1 and c-MYC was revealed." (PMID 35681778, 2022). "Here we identify oxidative phosphorylation (OxPhos) as a critical pathway for leukemia cell survival and demonstrate a direct relationship between NOTCH1, elevated OxPhos gene expression, and acquired chemoresistance in pre-leukemic and leukemic models." (PMID 35589701, 2022). "Overexpression of the active form of Notch1 or Notch2 in the human KCL‐22 leukaemia cell line has been reported to inhibit proliferation, accompanied by an increase in Hes1 mRNA levels." (PMID 35122387, 2022). "It has been demonstrated experimentally that PHF6 loss can enhance the oncogenic activity of NOTCH1 mutations; therefore, PHF6 and NOTCH1 co-mutation are more tightly linked to T-ALL pathogenesis and leukemia-associated mortality." (PMID 35280829, 2022). "The proliferation, invasion and apoptosis of leukemia cells can be controlled by miR-200b through its regulatory of NOTCH1 signaling pathway." (PMID 35889314, 2022).
leukemia (continued). "Using Cd3e-/- mice in which pre-TCR function is abrogated, we now show that oncogenic Notch1 controls disease penetrance in SCL-LMO1-induced T-ALL while the pre-TCR signal governs the time of leukemia onset." (PMID 35401501, 2022). "Insight into this question came when it was revealed that alternative transcription initiation sites are used at the Notch1 gene in Ikzf1-/- and E2a-/- leukemias." (PMID 35514954, 2022). "In T-ALL, mTORC2 was shown, like CCR7, to be downstream in the Notch-1 signaling pathway that activated the Akt-dependent NF-κB pathway to modulate leukemia cell survival." (PMID 35203305, 2022). "In TALL1 cells, Notch1 directly inhibited ATM kinase activity, thus contributing to the survival of Notch1-driven leukemias." (PMID 36497257, 2022). "While many investigations reported the different aspects of tumor cell growth and leukemia progression controlled by Notch1, less is known regarding the modifications of cellular metabolism induced by Notch1 upregulation in T‐ALL." (PMID 33314742, 2021). "The mechanistic link observed between Notch1 and mTORC1 through glutaminolysis seems to operate as a mechanism to potentiate cell growth and leukemia proliferation, sustaining high glutamine catabolism and high mTORC1 activity." (PMID 33314742, 2021). "For instance, an in vivo study using T‐ALL mouse models reported that glutaminolysis plays a critical role in leukemia progression downstream of Notch1." (PMID 33314742, 2021). "The role of TAL1 in hematopoiesis, leukemia, and endothelial cell generation is well-known, yet this is the first demonstration of Notch1-induced expression of TAL1 in GSCs." (PMID 34771555, 2021). "Our results placed glutamine limitation and mTORC1 inhibition as a potential therapy against Notch1‐driven leukemia." (PMID 33314742, 2021). "Notch1 activates IL7r transcription in human hematopoietic progenitors, as well as in murine leukemia cells." (PMID 34394130, 2021). "Further supporting its leukemia-initiating tumor suppressor role, inactivating Phf6 in hematopoietic progenitors, favors the development of NOTCH1-induced T-ALL." (PMID 34440292, 2021). "We next investigated if glutamine starvation and RAP treatment exerted a synergistic effect in the induction of cell death in Notch1‐positive leukemia." (PMID 33314742, 2021). "In T-ALL, Notch1 directly inhibited ATM kinase activity contributing to survival of Notch1-driven leukemias through impaired formation of FOXO3a-KAT5/Tip60 complex." (PMID 34680255, 2021). "For NOTCH1-dependent cells, the combination of both inhibitors was highly effective, strongly inhibiting leukemia proliferation and/or inducing cell death." (PMID 34167562, 2021). "Gain of function studies on transgenic animal models of T-ALL highlighted the role of Notch1 on leukemia initiating cells (LIC)." (PMID 32796631, 2020). "This was confirmed by the observation of accelerated leukemia development upon introducing PHF6 mutations in NOTCH1-driven murine T-ALL models, partly by elevating the leukemia stem cell numbers." (PMID 33251223, 2020). "Among the upregulated miRNAs was miR-709, which was previously reported as a tumor suppressor miRNA in the context of NOTCH1-induced leukemia." (PMID 32708470, 2020). "NOTCH1 pathway is also a central driver of T-cell metabolism and promotes leukemia cell growth via direct upregulation of anabolic pathways, including ribosome biosynthesis, protein translation and nucleotide and aminoacid metabolism." (PMID 32185137, 2020). "Growing evidence points out at the importance of the cross-talk between leukemia cells and the stromal microenvironment, as BMSCs show induced upregulation of Notch1, Notch3 and Notch4 as well as Jag1, Jag2 and Dll1." (PMID 32796631, 2020). "Many NOTCH1 and FBXW7 mutations observed in the primary leukemias were also present in the relapse samples." (PMID 33225950, 2020). "In Notch-1-dependent leukemia, SERCA activity was found to be required for progress of the cell cycle." (PMID 32575848, 2020).
leukemia (continued). "WGS studies identified non‐coding recurrent mutations, including the 3′‐UTR of NOTCH1 and a PAX5 enhancer, resulting in significant activity alterations of these transcription factors genes of well‐known importance in leukemia and other malignancies." (PMID 30520556, 2019). "Because FBXW7 mutations affect the stability of NOTCH1 and MYC proteins, this model was characterized by a marked increase of leukemia initiating cells (LIC), due to a greater MYC protein concentration." (PMID 31226848, 2019). "An emerging group of NOTCH1-independent TAL/LMO-positive leukemias harboring MYC translocations (constituting around 1–6% of adult and childhood T-ALL cases) has been recently described." (PMID 30304769, 2018). "Different lncRNAs takepart in normal lymphoid cell development, but variousexperiments have shed light on some lncRNAs likeLUNAR1 and NALT that, by interacting with NOTCH1,lend a hand in leukemia development." (PMID 30930624, 2018). "Mutations in IL7R, FBXW7, and NOTCH1 were specific to myeloid-T MPAL and T-ALL, suggesting a strong functional role of these genes in T cell lineage leukemia." (PMID 29991687, 2018). "Using three individual normal thymus specimens as control, we further verified these findings in 11 Chinese T-ALL patient samples, and found that SHQ1 was generally more abundant in leukemia cells with enhanced NOTCH1 activation, as judged by ICN1 production." (PMID 30323192, 2018). "RNA-seq was used to compare T cells proliferating in response to virus with primary T-ALL leukemia induced with mutant Notch1 expression." (PMID 30140438, 2018). "Glutaminolysis was identified as an integral pathway for leukemia cell proliferation controlled by NOTCH1 and, therefore, a critical determinant of anti-NOTCH1 clinical efficacy." (PMID 30191140, 2018). "In cases 6116 and CUL76, multiple clones read out in the xenograft confirming the position of NOTCH1 as a subclonal driver and demonstrating multiple competing subclones in the leukaemia initiating cell compartment." (PMID 29556024, 2018). "Recent studies have shown that the KDM6A/UTX, which is responsible for demethylating H3K27me3, have cases of inactivating lesions and downregulation of this gene accelerates NOTCH1-driven leukemia in mice." (PMID 29034206, 2017). "The tumor suppressor role of these miRNAs was further established by a delayed leukemia onset after overexpression of miR-451 or miR-709 in the NOTCH1-sensitized mouse model." (PMID 28270163, 2017). "Using a PRDM14-FLAG mouse model, we show that PRDM14 binds within an intron of Notch1 prior to leukemia development." (PMID 27106930, 2016). "In normal bone marrow cells, Notch-1 expression has been reported to be very low compared with leukemia cells." (PMID 27233074, 2016). "RHOU is also functionally linked to Notch1 signaling in leukaemia, where T-ALL cell migration is stimulated by RHOU upregulation, leading to enhanced motility and dissemination of leukaemia cells." (PMID 27196083, 2016). "We then analyzed the mRNA expression of POFUT1 in various leukemia cells line and found that this directly correlated with Notch-1 expression." (PMID 27233074, 2016). "This study also reported Notch1-ICD expression in murine leukaemia initiating cells upregulating HES1 levels, which led to the repression of myeloid expansion." (PMID 25711903, 2015). "The in vivo results indicated that low concentrations of tetrandrine inhibited leukemia cells proliferation and induced autophagy and then facilitated their differentiation, by activating ROS and Notch1 signaling." (PMID 25797266, 2015). "This is exemplified by NOTCH1, which has been described as a dominant (and hence OG) gene in leukaemia, but was shown to be a TSG in solid cancers as well." (PMID 25903787, 2015).